OLFML1 (olfactomedin like 1)
Synonyms: UNQ564; ONT2; MVAL564
Tractability: Antibody: UniProt places it where antibodies can reach, with high confidence; UniProt predicts a signal peptide or a membrane-spanning region; its Gene Ontology location is reachable by antibodies, with medium confidence.
Gene: Protein-coding gene on chromosome 11 (7,485,362 to 7,512,897, forward strand). Ensembl gene ENSG00000183801.
Subcellular location: Secreted
Gene Ontology:
Biological process: signal transduction
Cellular component: extracellular region
Genetic constraint (gnomAD): Loss-of-function variants: 33 observed, 38.9 expected, observed/expected ratio (o/e) 0.85, 90% interval 0.64 to 1.13. The upper end of that interval is the gene's LOEUF score, 1.13, which puts it in group 4 of 6, group 1 being the genes least tolerant of losing a copy. Missense variants: 545 observed, 509.64 expected, observed/expected ratio (o/e) 1.07, 90% interval 1 to 1.15. Synonymous variants: 186 observed, 190.91 expected, observed/expected ratio (o/e) 0.97, 90% interval 0.86 to 1.1.
Homologues: Orthologues: chimpanzee OLFML1 (99% identical), macaque OLFML1 (99% identical), guinea pig OLFML1 (86% identical), rat Olfml1 (84% identical), mouse Olfml1 (47% identical). Paralogues in human: OLFML3 (32% identical), MYOC (24% identical), OLFML2A (23% identical), OLFML2B (23% identical), OLFM1 (23% identical), OLFM2 (22% identical), OLFM3 (21% identical), OLFM4 (19% identical), GLDN (15% identical).
Diseases named in the same sentence as OLFML1 in open-access papers:
OLFML1 is named in the same sentence as 8 diseases in open-access papers, as found by Europe PMC text mining. Sharing a sentence is not in itself a finding about the gene and the disease. The quoted sentences say what the papers report.
colorectal cancer (1 paper, 2025). A primary or metastatic malignant neoplasm that affects the colon or rectum. "To investigate the potential role of OLFML1 in the progression CRC, we integrated six colorectal cancer GEO databases (GSE71222, GSE21510, GSE17537, GSE128435, GSE64857 and GSE20970) to evaluate transcriptional levels of OLFML1." (PMID 40765816, 2025).
Insulin resistance (1 paper, 2019). Increased resistance towards insulin, that is, diminished effectiveness of insulin in reducing blood glucose levels. "Tumor protein D52-like 1 (TPD52L1), OLFML1, and MUC1 are novel biomarkers for the development of insulin resistance." (PMID 30678306, 2019).
non-alcoholic fatty liver disease (1 paper, 2025). "Olfactomedin proteins, such as OLFML1, are expressed throughout the brain, are key for the early development of the nervous system (neural crest), and are implicated in obesity and non-alcoholic fatty liver disease." (PMID 40813973, 2025).
prostate tumours (1 paper, 2015). "Several other genes at this locus, including CYB5R2, EIF3F, NLRP10, OLFML1 and OVCH2, were also found to be significantly expressed in prostate tumours in comparison with normal tissues." (PMID 26443449, 2015).
cancer (2 papers, 2021 to 2025). A tumor composed of atypical neoplastic, often pleomorphic cells that invade other tissues. "OLFML1 is found to be associated with cell proliferation and autonomy in human cancer cells." (PMID 34686207, 2021). "Despite these findings, the role of OLFML1 in cancer, particularly in CRC, remains poorly understood, and its potential contribution to tumor progression and stemness has yet to be fully elucidated." (PMID 40765816, 2025). "To further investigate the role of OLFML1 in maintaining cancer stemness, we conducted in vitro limiting dilution assays." (PMID 40765816, 2025). "Our findings reveal that OLFML1 expression is regulated by insulin-like growth factor 2 mRNA-binding protein 3 (IGF2BP3), a well-known RNA-binding protein implicated in cancer progression." (PMID 40765816, 2025). "Mechanistically, we revealed that OLFML1 activates the Hedgehog signaling pathway, a key regulator of cancer stemness 20, to promote CRC cell proliferation and enhance cancer stem cell properties." (PMID 40765816, 2025). "Notably, OLFML1 has been identified as a secreted glycoprotein that promotes cell cycle progression in human cancer cell lines under in vitro conditions." (PMID 40765816, 2025). "Additionally, OLFML1 inhibition weakens tumor-stroma interactions in the microenvironment, reducing protective factors that shield cancer cells." (PMID 40765816, 2025). "This highlights OLFML1 as a potential therapeutic target for disrupting cancer stemness in CRC." (PMID 40765816, 2025). "Subsequently, we treated OLFML1-overexpressing cells with the Hedgehog pathway inhibitor GANT61, which in turn, OLFML1-induced cell colony formation and enhanced cancer stemness was suppressed." (PMID 40765816, 2025). "Mechanistically, we demonstrate that IGF2BP3 stabilizes the expression of OLFML1 to activate the Hedgehog signaling pathway, thereby promoting CRC cell proliferation and enhancing cancer stemness." (PMID 40765816, 2025). "Olfactomedin-like 1 (OLFML1), a member of the olfactomedin (OLF) protein family, has recently garnered attention for its potential role in cancer biology 13-15." (PMID 40765816, 2025). "High expression of OLFML1 promotes CRC cell proliferation and cancer stemness." (PMID 40765816, 2025).
tumor (2 papers, 2015 to 2025). "Furthermore, simultaneous high expression of IGF2BP3 and OLFML1 was strongly associated with larger tumor size and advanced T stage in the TNM classification." (PMID 40765816, 2025). "Colony formation assays and tumor sphere formation assays revealed that OLFML1 knockdown significantly reduced the colony-forming ability and stemness promoted by IGF2BP3 overexpression." (PMID 40765816, 2025). "The results showed that OLFML1 expression was markedly higher in CRC tumor samples compared to normal mucosa." (PMID 40765816, 2025). "High co-expression of IGF2BP3 and OLFML1 was significantly correlated with larger tumor size and advanced T stage." (PMID 40765816, 2025). "From above, our findings indicate that OLFML1 is upregulated in CRC tissues and is closely linked to tumor progression and unfavorable patient outcomes." (PMID 40765816, 2025). "To validate these findings in vivo, we used subcutaneous xenograft models to assess the role of OLFML1 in tumor growth." (PMID 40765816, 2025). "The simultaneous high expression of IGF2BP3 and OLFML1 is associated with poor prognosis in CRC patients, as it promotes stemness, tumor growth, and progression." (PMID 40765816, 2025). "Given its upregulation in CRC and its role in promoting tumor proliferation and stemness, targeting OLFML1 could disrupt critical pathways driving tumor progression." (PMID 40765816, 2025). "In summary, these results demonstrate that OLFML1 is essential for CRC cell proliferation, anti-apoptotic activity, and tumor development, highlighting its potential as a key driver of CRC progression." (PMID 40765816, 2025). "This study represents the first comprehensive investigation into the role of OLFML1 in CRC, highlighting its critical involvement in tumor biology and its potential clinical relevance." (PMID 40765816, 2025). "This elevated expression of OLFML1 was positively correlated with larger tumor size, advanced T stage in the TNM classification, and poorer tumor differentiation." (PMID 40765816, 2025). "Inhibition of OLFML1 could synergize with chemotherapy or targeted therapies by disrupting key pathways involved in CSC maintenance, tumor survival, and therapy resistance." (PMID 40765816, 2025).
OLFML1 also shares sentences with these, for which no sentence is quoted: endometrial cancer (1 paper); Obesity (1).